EIF2AK3 (eukaryotic translation initiation factor 2 alpha kinase 3)
Description:
Metabolic-stress sensing protein kinase that phosphorylates the alpha subunit of eukaryotic translation initiation factor 2 (EIF2S1/eIF-2-alpha) in response to various stress, such as unfolded protein response (UPR). Key effector of the integrated stress response (ISR) to unfolded proteins: EIF2AK3/PERK specifically recognizes and binds misfolded proteins, leading to its activation and EIF2S1/eIF-2-alpha phosphorylation. EIF2S1/eIF-2-alpha phosphorylation in response to stress converts EIF2S1/eIF-2-alpha in a global protein synthesis inhibitor, leading to a global attenuation of cap-dependent translation, while concomitantly initiating the preferential translation of ISR-specific mRNAs, such as the transcriptional activators ATF4 and QRICH1, and hence allowing ATF4- and QRICH1-mediated reprogramming. The EIF2AK3/PERK-mediated unfolded protein response increases mitochondrial oxidative phosphorylation by promoting ATF4-mediated expression of COX7A2L/SCAF1, thereby increasing formation of respiratory chain supercomplexes. In contrast to most subcellular compartments, mitochondria are protected from the EIF2AK3/PERK-mediated unfolded protein response due to EIF2AK3/PERK inhibition by ATAD3A at mitochondria-endoplasmic reticulum contact sites. In addition to EIF2S1/eIF-2-alpha, also phosphorylates NFE2L2/NRF2 in response to stress, promoting release of NFE2L2/NRF2 from the BCR(KEAP1) complex, leading to nuclear accumulation and activation of NFE2L2/NRF2 (By similarity). Serves as a critical effector of unfolded protein response (UPR)-induced G1 growth arrest due to the loss of cyclin-D1 (CCND1) (By similarity). Involved in control of mitochondrial morphology and function (By similarity).
Synonyms: PEK; PERK; WRS
Tractability: Small molecule: a structure with a bound ligand is known; a high-quality ligand is known; it belongs to a druggable protein family. Antibody: UniProt predicts a signal peptide or a membrane-spanning region. PROTAC: ubiquitination databases record sites on it; its protein half-life has been measured; a small molecule that binds it is known.
Target class: Other protein kinase PEK subfamily; Enzyme; Other protein kinase group; Other protein kinase PEK family; Protein Kinase; Kinase
Chemical probes: AMG-PERK-44 (high quality), GSK2656157 (high quality)
Gene: Protein-coding gene on chromosome 2 (88,556,741 to 88,691,518, reverse strand). Ensembl gene ENSG00000172071.
Subcellular location: Endoplasmic reticulum membrane
Subcellular location (Human Protein Atlas): Cytosol; Nucleoplasm; Mitochondria
Pathways (Reactome):
Cellular responses to stimuli: KEAP1-NFE2L2 pathway; PERK regulates gene expression
Disease: ALK mutants bind TKIs; Signaling by ALK fusions and activated point mutants
Immune System: Modulation of host responses by IFN-stimulated genes
Gene Ontology:
Molecular function: enzyme binding; eukaryotic translation initiation factor 2alpha kinase activity; identical protein binding; misfolded protein binding; protein binding; protein kinase activity; protein phosphatase binding; protein serine kinase activity; protein serine/threonine kinase activity; protein tyrosine kinase activity; translation regulator activity; ATP binding; Hsp90 protein binding; non-membrane spanning protein tyrosine kinase activity
Biological process: angiogenesis; cellular response to amino acid starvation; cellular response to cold; cellular response to glucose starvation; endocrine pancreas development; endoplasmic reticulum unfolded protein response; ER overload response; ossification; PERK-mediated unfolded protein response; positive regulation of gene expression; positive regulation of transcription by RNA polymerase I; positive regulation of vascular endothelial growth factor production; regulation of endoplasmic reticulum stress-induced intrinsic apoptotic signaling pathway; response to endoplasmic reticulum stress; bone mineralization; calcium-mediated signaling; chondrocyte development; endoplasmic reticulum organization; insulin-like growth factor receptor signaling pathway; negative regulation of myelination; negative regulation of translation; negative regulation of translational initiation; negative regulation of translational initiation in response to stress; positive regulation of protein localization to nucleus; regulation of translation initiation in response to endoplasmic reticulum stress; and 4 more
Cellular component: endoplasmic reticulum; membrane; mitochondria-associated endoplasmic reticulum membrane contact site; cytoplasm; cytosol; endoplasmic reticulum membrane; nucleus; perinuclear region of cytoplasm
Genetic constraint (gnomAD): Loss-of-function variants: 42 observed, 89.69 expected, observed/expected ratio (o/e) 0.47, 90% interval 0.37 to 0.61. The upper end of that interval is the gene's LOEUF score, 0.61, which puts it in group 2 of 6, group 1 being the genes least tolerant of losing a copy. Missense variants: 876 observed, 1,036.2 expected, observed/expected ratio (o/e) 0.85, 90% interval 0.8 to 0.89. Synonymous variants: 335 observed, 367.23 expected, observed/expected ratio (o/e) 0.91, 90% interval 0.83 to 1.
Homologues: Orthologues: chimpanzee EIF2AK3 (99% identical), macaque EIF2AK3 (98% identical), dog EIF2AK3 (92% identical), pig EIF2AK3 (91% identical), guinea pig EIF2AK3 (90% identical), mouse Eif2ak3 (87% identical), rat Eif2ak3 (87% identical), rabbit EIF2AK3 (84% identical), tropical clawed frog eif2ak3 (69% identical), zebrafish eif2ak3 (58% identical), Drosophila melanogaster Wee1 (10% identical). Paralogues in human: EIF2AK4 (19% identical), EIF2AK2 (15% identical), EIF2AK1 (14% identical), WEE1 (10% identical), WEE2 (10% identical), STK35 (8% identical), PKMYT1 (7% identical), PDIK1L (7% identical).
Diseases named in the same sentence as EIF2AK3 in open-access papers:
EIF2AK3 is named in the same sentence as 448 diseases in open-access papers, as found by Europe PMC text mining. Sharing a sentence is not in itself a finding about the gene and the disease. The quoted sentences say what the papers report.
breast cancer (143 papers, 2007 to 2026). A primary or metastatic malignant neoplasm involving the breast. "EIF2AK3 has been identified as an immune-related prognostic gene in breast cancer, exerting a role in tumor cell apoptosis and facilitating sustained protective antitumor immunity." (PMID 38167084, 2024). "Consistent with our results, a recent study showed that the two eIF-2α kinases, eIF2AK3 and eIF2AK4, contributed to paclitaxel response in breast cancer." (PMID 32615282, 2020). "In addition, it has been reported that UA induces endoplasmic reticulum (ER) stress and autophagy in MCF-7 human breast cancer cells, and autophagy-dependent endoplasmic reticulum stress protects cells from UA-induced apoptosis through EIF2AK3-mediated MCL1 upregulation." (PMID 37190306, 2023). "Therefore, the ISR in breast cancer cells after paclitaxel treatment may be induced by a co‐ordinated effect conferred by EIF2AK3 and EIF2AK4." (PMID 31211507, 2019). "Here, we showed that paclitaxel, the major chemotherapy drug for breast cancer, induced ISR and phosphorylated ser51 residue of EIF2S1 by EIF2AK3 and EIF2AK4." (PMID 31211507, 2019). "In breast cancer, the expression of PERK (EIF2AK3) was down-regulated, but its activity was shown to be constitutionally elevated in drug-resistant cells, and it was found that PERK could be a potential target for drug-resistant cancer therapy." (PMID 36178365, 2022). "Importantly, the RNA sequencing data on ERO1 KO MDAMB23* breast cancer indicate an increase in UPR and specifically in ER‐resident kinase PERK (eIF2AK3) branch, suggesting activation of the PERK arm of the UPR." (PMID 35853086, 2022).
diabetes (116 papers, 2007 to 2026). "Genetic mutations in EIF2AK3, the gene that encodes PERK, are causatively associated with Wolcott–Rallison syndrome—a devastating disease characterized by early onset diabetes, skeletal deformities, and growth impairments." (PMID 37306086, 2023). "Wolcott-Rallison syndrome is a rare cause of permanent neonatal diabetes mellitus caused by mutations in the eukaryotic translation initiation factor 2 alpha kinase 3 gene (EIF2AK3)." (PMID 37873802, 2023). "As an example of a DMR only identified by unique-included analysis, we plotted a region within the Eif2ak3 gene, whose variants have been associated with Wolcott-Rallison syndrome and diabetes." (PMID 31392989, 2019). "The three patients with Wolcott–Rallison syndrome (WRS), due to homozygous EIF2AK3 mutations, were from consanguineous families and they presented with diabetes at a median age of 85 days (range 66–96 days)." (PMID 25755231, 2015). "Wolcott-Rallison syndrome (WRS) is caused by recessive EIF2AK3 mutations and characterized by early-onset diabetes and skeletal dysplasia." (PMID 25659842, 2015). "Children with WRS typically present in the first few months of life with diabetes, and it is recommended that any child of consanguineous parents presenting with diabetes within the first 6 months of life should be tested for EIF2AK3 mutations." (PMID 25659842, 2015). "PERK (EIF2AK3) loss of function mutations in humans and mice exhibit permanent neonatal diabetes that is characterized by insufficient β-cell mass and reduced proinsulin trafficking and insulin secretion." (PMID 24915520, 2014). "As the most common cause of PNDM, any neonatal case of diabetes mellitus, in particular among consanguineous parents is a real candidate for molecular analysis of EIF2AK3 gene." (PMID 24032041, 2013). "Since the first child was died, a single proband was tested for EIF2AK3 mutation with a suspected diagnosis of Wolcott-Rallison Syndrome based on early-onset diabetes (within the first 15 months of age), unexplained liver dysfunction, and skeletal dysplasia." (PMID 24032041, 2013). "Furthermore, the reduction of EIF2AK3-EIF2α signaling has been observed to result in the development of diabetes phenotypes in mouse models of EIF2AK3 deficiency." (PMID 39000233, 2024). "For example, heterozygous deletion of Eif2ak3 in Akita mutant mice (which develop β cell loss and diabetes owing to a mutation in proinsulin that cripples its folding) significantly delays diabetes onset, a phenotype replicated by use of low-dose PERK inhibitors in these mice." (PMID 38889047, 2024). "Although the mechanism causing diabetes is unclear, defects in EIF2AK3 may cause ER stress in the β-cell from misfolded proteins due to the high demand for insulin secretion, eventually leading to β-cell apoptosis." (PMID 28049534, 2017). "Alternatively, diabetes may be linked to reduced β-cell proliferation with abnormal insulin trafficking and secretion, as observed in EIF2AK3 knockout mice." (PMID 28049534, 2017). "Studies in EIF2AK3/PERK knockout mouse demonstrated that PERK is required for pancreatic beta cell development during fetal and early neonatal development, and that diabetes and skeletal dysplasia are due to loss of PERK expression in pancreatic beta cells and osteoblasts." (PMID 23759358, 2013). "Defect in EIF2AK3 results in a permanent diabetes in early infancy or newborn period, a tendency to develop skeletal fractures and other associated disorders such as severe liver and renal dysfunction, and central hypothyroidism." (PMID 34123975, 2021). "Among these interactors, EIF2AK3, GLIS3, IER3IP1, and PLAGL1 are linked to Diabetes mellitus in Swiss-Prot." (PMID 34715892, 2021). "The Wolcott-Rallison syndrome results from mutations in PERK (EIF2AK3), leading to permanent neonatal diabetes due to β-cell ER stress." (PMID 30412050, 2018). "Analysis of known neonatal diabetes genes, including EIF2AK3, did not identify a likely causative variant." (PMID 36704923, 2023).
diabetes (continued). "Biallelic mutations in the EIF2AK3 gene (encoding PERK) and dominant mutations in EIF2B1 (resulting in loss of sensitivity of the EIF2B complex to eIF2α phosphorylation) result in syndromic forms of neonatal/early onset diabetes and likely β-cell death." (PMID 33967960, 2021). "Furthermore, in humans, mutations in the EIF2AK3 gene, which encodes PERK, causes Wolcott–Rallison syndrome, which is characterized by permanent neonatal or early infancy diabetes because of impaired insulin secretion." (PMID 28208663, 2017). "In addition to NKX6–1 we found variants in WFS1, RFX6 and 7 other genes associated with monogenic forms of diabetes (AKT2, EIF2AK3, GLIS3, HADH, MNX1, NKX2–2, and PTF1A) and they may be relevant to development of MODY." (PMID 29439679, 2018). "Heterozygous carriers of EIF2AK3 mutations do not present with diabetes." (PMID 28951826, 2017). "Several monogenic diabetes genes target translational initiation, in particular eIF2 complex (EIF2B1, EIF2S3, EIF2AK3), due to their impact on endoplasmic reticulum stress in β-cells." (PMID 36109769, 2022). "The number of variants detected was greater than in Stage 1 since five additional monogenic diabetes genes (CEL, EIF2AK3, ABCC8, BLK, and KLF11) were sequenced." (PMID 29207974, 2017). "In permanent neonatal diabetes (PNDM) patients, homozygous GCK (n=6), EIF2AK3 (n=3), PTF1A (n=3), and INS (n=1) and heterozygous KCNJ11 (n=2) mutations were identified." (PMID 25755231, 2015).
melanoma (109 papers, 2007 to 2026). A malignant, usually aggressive tumor composed of atypical, neoplastic melanocytes. "PERK-dependent signaling might be affected due to an inframe deletion in EIF2AK3 leading to a PERKL21del variant that was found in all melanoma cell lines." (PMID 30989459, 2019). "This might result from an inframe deletion in EIF2AK3 leading to a PERKL21del variant revealed by whole-exome sequencing in melanoma cell lines." (PMID 30989459, 2019). "We observed in four independent mouse models of melanoma (N = 6–13 mice per model) that Perk (Eif2ak3) transcription was negatively correlated with Kdelr3 transcription, whereas Gadd34 (Ppp1r15a) transcription was positively correlated." (PMID 31949145, 2020). "In this study, we determined that PERK (protein kinase RNA-like endoplasmic reticulum kinase, or EIF2AK3), an ER stress sensor, is an essential mediator associated with resistance to BRAFi in melanoma with inactivated PTEN." (PMID 34282258, 2021). "The potential mechanism involves the upregulation of PERK (EIF2AK3), inhibition of which restores the sensitivity of PTEN-impaired melanoma cells to BRAF inhibitor." (PMID 35565444, 2022).
viral infection (108 papers, 2009 to 2025). "The ISR is activated in response to many different types of cellular stress (including amino acid starvation and viral infection) and is mediated by four different cellular kinases, EIF2AK1 (HRI), EIF2AK2 (PKR), EIF2AK3 (PERK) and EIF2AK4 (GCN2)." (PMID 39951426, 2025). "The map illustrates that HSPA8 and proteins in subnetworks, such as EIF2AK3, TLR4, NFKB1, BAK1, and RelA, are enriched in viral infection of several viruses." (PMID 34769416, 2021). "EIF2AK3/PERK is activated by unfolded proteins in the endoplasmic reticulum and responds to metabolic stress, viral infection and hypoxia." (PMID 30533021, 2018). "In addition to GCN2, there are three other mammalian eIF2α kinases: PERK (EIF2AK3/PEK), PKR (EIF2AK2) and HRI (EIF2AK1), which are activated by endoplasmic reticulum (ER) stress, viral infection, and heme deprivation in reticulocyte cells, respectively." (PMID 31194856, 2019).
colorectal cancer (59 papers, 2010 to 2026). A primary or metastatic malignant neoplasm that affects the colon or rectum. "EIF2AK3-mediated ER stress has been linked to increased autophagy in tumor tissues, such as in colorectal cancer." (PMID 41353169, 2025). "In colorectal cancer cells, the ATF6 transcriptionally active N-terminus increased GRP78, DDIT3 (which encodes CHOP), and EIF2AK3 (which encodes PERK) gene expression and significantly increased apoptotic cells." (PMID 38283278, 2023). "EIF2AK3 (tumour-activating protein kinase R (PKR)-like endoplasmic reticulum kinase) is also known as PERK, and its inactivation leads to an increase in ferroptosis in colorectal cancer cells." (PMID 38321105, 2024).